NF1 (neurofibromin 1)
Diseases named in the same sentence as NF1 in open-access papers (continued):
Sharing a sentence is not in itself a finding about the gene and the disease.
melanoma (continued). "According, DANCR is highly expressed across all four melanoma genomic subtypes (NRAS, NF1, BRAF, and triple negative) in The Cancer Genome Atlas (TCGA) genomic and transcriptomic data and in all melanoma cell subpopulations within a heterogeneous tumour model." (PMID 41336739, 2025). "The impact of tovorafenib on in vivo antitumor activity was assessed in an AGK::BRAF fusion melanoma PDX model and in two NF1-LOF models, including an ERMS PDX and the MeWo melanoma xenograft." (PMID 40111124, 2025). "In 2015, the Cancer Genome Atlas Program (TCGA) Network suggested a new genomic classification for melanoma: mutant BRAF (31%), mutant RAS (18%), mutant NF1 (21%), and triple WT (26%)." (PMID 39126091, 2024). "Consistent with this, in three melanoma datasets examined, module #35 was higher in RAS/RAF/NF1-mutant than triple-wild type samples." (PMID 38791964, 2024). "From the six primary tumors, we were able to obtain PDOX models for each engrafted tumor and, in addition, three new cell lines, two from NF1‐MPNST tumors (NF1‐08 and NF1‐09), and one from the sporadic tumor SP‐01, a suspected melanoma." (PMID 37798904, 2024). "The authors also analyzed specific genomic profiles within those four melanoma types using previously identified The Cancer Genome Atlas (TCGA) molecular categories: BRAF+, RAS+, NF1+, and triple negative." (PMID 39340537, 2024). "HBL cells belong to the triple-WT molecular subtype of melanomas (NRAS, BRAF and NF1 WT) and they respond to stimulation with melanocortin agonists with strong increases in both cAMP and ERK1 and ERK2 activity." (PMID 37762683, 2023). "In 2015, researchers from the Cancer Genome Atlas Network (TCGA) classified melanoma into four major molecular subtypes: BRAF, RAS (N/H/K), NF1, and Triple-WT, with the first three subtypes resulting in a permanent activation of the MAPK/ERK." (PMID 37174072, 2023). "The genetic makeup of the triple-wild-type melanoma (BRAF, NRAS and NF1) has been known for some time, but those studies grouped together rare histopathological versions with common ones, as well as mucosal and even uveal ones." (PMID 36980598, 2023). "The first-in-human (FIH) study of FCN-159 in melanoma (FCN-159-001) and a phase I/II trial in NF1 (FCN-159-002) demonstrated promising anti-tumor effects and tolerability in adult patients with NRAS mutant solid tumors." (PMID 36755948, 2023). "Molecular testing for common melanoma driver genes, including BRAF, NRAS, KRAS, HRAS, NF1, and KIT, was available for this study." (PMID 37686691, 2023). "According to the molecular characteristics based on TCGA data for cutaneous melanoma, melanoma can be divided into four subtypes, namely, the BRAF, RAS, NF1 and triple- wild- type subtypes." (PMID 37277447, 2023). "This analysis led to the identification of 266 loops between 66 significantly screened enhancers via CRISPRi and 200 target genes, of which some have been previously recognized to play a critical role in constraining melanoma development (e.g., PTEN, NF1)." (PMID 37904237, 2023).
melanoma (continued). "Currently, four genomic subgroups of melanoma have been identified through studies of The Cancer Genome Atlas (TCGA) network: BRAF (B-rapidly accelerated fibrosarcoma), NRAS, NF1, and triple wild type." (PMID 37446286, 2023). "BRAF, RAS and NF1 proteins are involved in the MAPK signalling pathway, which is often deregulated in melanoma, resulting in stimulation of cell proliferation and survival." (PMID 36765773, 2023). "Class I enhancers are frequently lost in melanoma patients including some that are functional towards classical tumor suppressor genes (e.g., PTEN, NF1)." (PMID 37904237, 2023). "A high-resolution CRISPR screen of non-coding functional elements surrounding three genes, including NF1, NF2, and CUL3, uncovered several critical CREs that modulate drug resistance in melanoma." (PMID 37904237, 2023). "To examine the effect of KDs on melanoma growth, we established BRAF mutant (A375 and WM47), BRAF/NRAS/NF1 wild-type (WM3311), and NRAS mutant (WM3000) xenografts in CD-1 nude mice." (PMID 35851093, 2022). "Similar to the traditional histological subclassification of melanoma, today the molecular classification is also possible where there are four major categories, the BRAF-mutant, the RAS-mutant, the NF1-mutant and the so-called triple wild-type forms." (PMID 35628196, 2022). "Consistent with a key role of RAS in the orchestration of drug resistance in melanoma, NF1 was the top hit in a large-scale short hairpin RNA (shRNA) screen for genes that, when lost, confer resistance to BRAF inhibition in melanoma cell lines." (PMID 35234863, 2022). "We found PRRT3-AS1 was significantly highly expressed in melanoma, BRAF, NF1, RAS mutants, and Triple WT tissues, whereas DANCR showed limited expression difference." (PMID 36211371, 2022). "miR-514a-3p was further described to regulate the tumor suppressor NF1 and to be involved in BRAF inhibitor sensitivity in melanoma." (PMID 34073664, 2021). "As melanoma is characterized by activation of MAPK signaling due to mutations in BRAF, NRAS, NF1 and KIT genes, this suggests that further hyperactivation of MAPK signaling through loss of inhibitors of this signaling pathway may be deleterious to melanoma cells." (PMID 32767816, 2021). "As a result, melanomas have been classified into four distinct genetic subsets based on the molecular signature (BRAF mutant, NRAS mutant, NF1 mutant, and triple negative)." (PMID 34831002, 2021). "Based on the pattern of mutated genes, a genomic classification of melanoma has been established and melanomas have been classified into four subtypes: mutant BRAF, mutant RAS, mutant NF1, and Triple-WT (wild-type)." (PMID 34698264, 2021). "Genetic alterations in BRAF and NRAS, as well as a handful of tumor suppressors such as NF1, CDKN2A, ARID2 and PTEN, have been shown to contribute to melanoma pathogenesis." (PMID 33958721, 2021). "Human NF1-mutant melanomas have the worst outcome among all metastatic melanomas, and PTEN-mutant melanomas are known to be resistant to T-cell mediated immunotherapy such as the immune checkpoint inhibitor." (PMID 34331013, 2021). "The Cancer Genome Atlas (TCGA) classified cutaneous melanomas into four molecular subtypes: BRAF-mutant (47.5%), RAS-mutant (29%), NF1-mutant (9%), and triple-wild type (14.5%)." (PMID 34331013, 2021). "This cohort study found that among patients with NF1, those who developed undifferentiated pleomorphic sarcoma, HGG, MPNST, ovarian carcinoma, or melanoma had significantly lower DSS rates compared with those who developed other neoplasms." (PMID 33734413, 2021). "Malignant melanoma has been classified in four subgroups according to its main genetic drivers by The Cancer Genome Atlas: mutant BRAF, mutant NRAS, mutant NF1, or triple wild-type tumors." (PMID 34362135, 2021).
melanoma (continued). "Of these, one had a BRAF mutant melanoma (ETH-E), two had NRAS mutant melanomas (SK-G & ETH-J), and three were BRAF/NRAS/NF1 wild-type (MI-F, SK-H, ETH-F)." (PMID 33664264, 2021). "A whole-genome study of 183 melanomas found RAF1 fusions in two melanomas (with partners CDH3 and GOLGA4): one triple wild type and one with an NF1 comutation." (PMID 32123303, 2020). "This signaling cascade is constitutively active in the majority of melanomas as a result of genetic alterations in BRAF, RAS or NF1 (neurofibromin 1)." (PMID 31659567, 2020). "In the era of precision medicine, it is important to characterize melanoma tumors through molecular subtypes and to identify targeted therapies that are best suited for these subtypes—BRAF, RAS, NF1, and triple wild-type." (PMID 33256089, 2020). "A similar finding has been reported with resistance to BRAF inhibitors in NF1-mutant and BRAF-mutant melanomas, yet the tumors were sensitive to combined inhibition of MEK and mTOR." (PMID 31906320, 2020). "Of the activating RAF1-fusion melanomas, 98% (n = 39) were wild type for BRAF, NRAS, and NF1 genomic alterations (triple wild type) vs. 26% (n = 1843/7079) of the melanoma cohort without RAF1 fusion (p < 0.0001, Fisher’s exact test)." (PMID 32123303, 2020). "All the melanomas were classed into 4 group (BRAF, RAS, NF1, and Triple-WT) based on their major cancer driver genes." (PMID 32083130, 2020). "ShRNA-mediated knockdown of CAPN1 or treatment with a CAPN1 inhibitor showed to stabilize NF1 protein levels, downregulate AKT signaling and melanoma cell growth." (PMID 32850962, 2020). "MiR-514a, a well-known key player in initiating melanocyte transformation and enhancing melanoma growth, has been reported to regulate the sensitivity of BRAF-targeted therapy by modulating the tumor suppressor NF1 gene." (PMID 32013263, 2020). "The chemotherapy of melanoma depends on four genetic types: including mutant BRAF, mutant RAS (N/H/K), mutant NF1, and Triple wild-type." (PMID 31380151, 2019). "We have investigated the impact of signaling by RAC1, an oncogene which is mutationally activated in 4% of melanomas and may be activated by alterations in upstream regulators in a larger fraction, showing that RAC1P29S promotes the initiation of melanoma driven by mutant BRAF or NF1 loss." (PMID 31257073, 2019). "While we also observed a high recall for BRAF, NF1, and TWT drug combination predictions, we found a lower recall (0.29) specifically for the IPC-298 NRAS-mutant melanoma cell line." (PMID 30820351, 2019). "Based on genomic analyses of the most prevalent mutations in the tumors (significantly mutated genes), the TCGA Research Network classified four molecular subtypes for melanoma patients: mutant BRAF, mutant RAS, mutant NF1, and Triple-Wildtype." (PMID 31747929, 2019). "We employed SynGeNet to generate drug combination predictions for each of the four major genomic subtypes of melanoma (BRAF, NRAS, NF1, and triple wild type) using publicly available gene expression and mutation data." (PMID 30820351, 2019). "DMs also tend to have lower DNA copy number alterations than other melanoma subtypes; the few focal deletions that have been observed target CDKN2A and NF1, whereas amplifications affect EGFR, CDK4, MDM2, TERT, MAP3K1, MET, YAP1 and NFKBIE13." (PMID 30511391, 2019). "Melanomas which are wild type for BRAF, NRAS, and NF1 show amplifications of KIT, platelet-derived growth factor receptor α (PDGFRA), and vascular endothelial growth factor receptor 2 (VEGFR2) in 10–20% of cases." (PMID 30987166, 2019). "Many of the SV events targeted well-known melanoma driver genes (CDKN2A, NF1, PTEN, and TERT), exemplifying their role in mucosal melanoma pathogenesis." (PMID 31320640, 2019).
melanoma (continued). "ShRNA-mediated knockdown of CAPN1 or treatment with a CAPN1 inhibitor stabilizes NF1 protein levels, downregulates AKT signaling and melanoma cell growth." (PMID 30131853, 2018). "Most melanomas harbor alterations in the BRAF, NF1, RAS, MDM2 (KIT) genes, which result in activation of the MAPK and RAS pathways conferring survival advantage by reprogramming crucial cell cycle and apoptotic cellular functions." (PMID 28445515, 2017). "Here, we show that the EPE peptide not only reduces the growth of many BRAF mutant melanomas, but also several NRAS and NF1 mutant melanomas, insensitive to BRAF inhibition." (PMID 29180761, 2017). "However, the precise prevalence of melanomas in NF-1 patients is largely unknown." (PMID 15363097, 2004). "Uveal melanoma is an uncommon and special subtype of melanoma with a unique mutation landscape, lacking NRAS, BRAF, and NF1 mutation." (PMID 41492362, 2026). "Thus, Cobi+Reg produced marked antitumor efficacy in multiple PDX lines encompassing the major molecular subtypes of melanoma (i.e., BRAF-, NRAS-, and NF-1–mutant) developed after progression on PD-1–based ICB." (PMID 40638246, 2025). "Of the 56 tumours with Class II mutations, six (10.7%), all classified as melanoma, had additional MAPK pathway mutations, including BRAFK601E, BRAFG469A, NRASQ61K, NRASG12D, HRASQ61K, and NF1W1559∗ (NF1 was not included in the NGS panel for 16 tumours)." (PMID 40107205, 2025). "We then compared gene expression in the intradermal melanomas and sparse pigment tumors, irrespective of Nf1 genotype, in order to better define their differences." (PMID 39804140, 2025). "Lastly, the TWT melanoma subtype is characterized by the absence of mutations in the three most common melanoma driver genes, namely BRAF, NRAS, and NF1." (PMID 40867277, 2025). "For example, triple wild-type melanomas, which are melanomas lacking mutations in BRAF, NRAS, and NF1, exhibit markedly low TMB compared to NF1-mutant melanomas." (PMID 40004731, 2025). "In that case, the non-NF1 patient, who had a history of non-melanoma skin cancer, developed melanoma at the site of a cluster of cNFs." (PMID 39687068, 2024). "The most common mutations in CSD and non-CSD melanomas affect BRAF, NRAS, and NF1 genes governing proliferation through action on the MAPK pathway, with BRAF and NRAS defined as oncogenes and NF1 as tumor suppressor gene." (PMID 38927967, 2024). "Driver mutations of a conventional melanoma, such as BRAF, NRAS, or NF1, should not be seen in the Spitz family." (PMID 38247727, 2024). "We lastly examined whether the distribution of short (<10 kb) INVs and DELs observed in NF1- and (N)RAS-mutant melanomas was the result of chromothripsis." (PMID 38758740, 2024). "Loss of NF1 also occurs in 5% of all sporadic tumors, including glioblastoma multiforme (GBM), breast cancer, endometrial cancer, ovarian cancer, both melanoma and non-melanoma skin cancers, and lung cancer." (PMID 39016685, 2024). "Triple WT melanomas are characterized by the absence of mutations in these three genes (BRAF, RAS, and NF1)." (PMID 39126091, 2024). "In classical NF1 and melanoma, but not 3bp deletion NF1, there was also activation of the PI3K/AKT pathway." (PMID 39355740, 2024). "With regard to anatomic location, NF1 mutant tumors (n = 22/47, 46.8%), TWT melanomas (n = 14/33, 42.4%) and co-mutant tumors (n = 7/20, 35%) occurred more frequently on the head/neck compared with BRAF or NRAS mutant tumors (n = 24/154, 15.6%; p < 0.001, chi-squared test)." (PMID 38611025, 2024).
melanoma (continued). "Acral melanomas, having no direct association with sun exposure, although having mutations in BRAF, NRAS, NF1, and KIT, show a lighter and different mutational burden in comparison to low-CSD or high-CSD melanomas." (PMID 38927967, 2024). "Moreover, activation of BRAF and RAS as well as NF1 can subsequently activate the MAPK signaling pathway, the most important pathway mediating melanoma metastasis." (PMID 37277447, 2023). "The category of melanomas with “little or no UV/CSD exposure” rarely harbor BRAF, NRAS, or NF1 mutations." (PMID 37174072, 2023). "We devised a strategy based on CRISPR-Cas9 knockout of endogenous MC1R in a human melanoma cell line wildtype for BRAF, NRAS and NF1, followed by reconstitution with epitope-labeled MC1R constructs, and functional analysis of clones expressing comparable levels of wildtype, R151C or D294H MC1R." (PMID 37762683, 2023). "In accordance with the published data, the three ALM melanomas in our cohort were not BRAF mutated; rather, they carried NRAS, KIT and NF1 mutations." (PMID 36765773, 2023). "On the hand in conventional melanomas, resembling Spitz tumors or not, the initiating event is the involvement of BRAF, NRAS, KIT or NF1 mutations." (PMID 38031947, 2023). "Similarly, PTEN, NF1, KLF6, and THBS1 genes were frequently reported in different cancer gene resources as melanoma tumor suppressors." (PMID 37904237, 2023). "Most melanoma patients have non-overlapping “driver” mutations in either BRAF, NRAS, or NF1 genes based on Next-Gen sequencing." (PMID 37444637, 2023). "Although melanomas with RAF1 fusions are seldom observed (less than 1%), clinical sample analyses have consistently shown that melanomas harboring RAF1 fusions exhibit wide-type status for BRAF, RAS, and NF1." (PMID 38111008, 2023). "In our dataset, melanomas with FER amplification had frequent NF1 inactivation but lacked BRAF and NRAS alterations." (PMID 35706047, 2022). "For example, the progression from a dysplastic nevus to the RGP occurs as a result of unchecked mutations and epigenetic changes in cell cycle and cell survival regulators including PTEN, NF1, CDKN2A, and CCND1 that allow the melanoma cells to bypass senescence." (PMID 36119516, 2022). "Desmoplastic melanomas have fewer DNA copy number alterations than other melanoma subtypes; nevertheless, the few focal deletions that have been observed targeting CDKN2A and NF1." (PMID 34441278, 2021). "Previous genome-scale sequencing studies have identified mutations in a number of genes involved in the initiation and progression of melanoma, including BRAF (50%), NRAS (20–30%), neurofibromin 1 (NF1) (10–15%), and cyclin-dependent kinase inhibitor 2A (CDKN2A) (20–40%)." (PMID 34771678, 2021). "According to the whole-exome sequence analysis of melanoma patients carried out by The Cancer Genome Atlas (TCGA), the following four main melanoma mutants can be identified: BRAF, Neuroblastoma Rat Sarcoma (NRAS), Neurofibromatosis type 1 (NF1) and Triple-wild-type." (PMID 34683910, 2021). "BRAF fusions in mucosal melanomas have also been described, with a comparable frequency as of cutaneous triple wild type melanoma (i.e., lacking BRAF, NRAS, and NF1 mutations)." (PMID 35008570, 2021). "None of the cases were found to harbor BRAF, NF1 and PDGFRA mutations in melanomas of the female genital tract." (PMID 34102999, 2021).